FUBP1 (far upstream element binding protein 1)
Diseases named in the same sentence as FUBP1 in open-access papers (continued):
Sharing a sentence is not in itself a finding about the gene and the disease.
cancer (continued). "Next, the expression of FUBP1 in various cancers in TCGA was analyzed using TIMER2." (PMID 35274005, 2022). "As mentioned, FUBP1 is a potential cancer-promoting regulator in a variety of tumors." (PMID 35546072, 2022). "Subgroup analyses of different cancers were also conducted, and the results further verified that although high FUBP1 expression correlates with poor prognosis in most cancer types in TCGA, differences are observed depending on the cancer type and even the subtype." (PMID 35274005, 2022). "The function of FUBP1 in various cancers raises growing interest." (PMID 35546072, 2022). "The KEGG analysis suggested that the oncogenic role of FUBP1 in different cancers might involve the “spliceosome” (p = 9.2e−25, 22 genes included) and “mRNA surveillance” (p = 3.1e−3, 5 genes included) pathways." (PMID 35274005, 2022). "However, no pan-cancer analyses have been conducted to explore the relationship between FUBP1 expression and various cancer types based on clinical data." (PMID 35274005, 2022). "This study was the first multifaceted investigation examining the FUBP1 gene and protein in all cancers found in TCGA, including the mRNA expression level, survival correlation, mutation, phosphorylated protein, surrounding immune environment, enriched partners and related signaling pathways." (PMID 35274005, 2022). "Moreover, alterations in FUBP1 were found to be closely related to overall survival in pan-cancer according to TCGA datasets." (PMID 35274005, 2022). "Given that the nuclear localization of FUBP1 crucially affects the transcription of oncogenes, we speculated that blocking the nuclear import of FUBP1 suppresses cancer proliferation and becomes a potential target for cancer therapy." (PMID 33987449, 2021). "FUBP1 codes for the far upstream binding protein 1 (FUBP1 also named FBP1), which has an important role in cell proliferation and is implicated in multiple types of cancers." (PMID 24086756, 2013). "Notably, the relevance of FUBP1 and c-Myc expression in several cancers suggests that FUBP1 may play a role in the carcinogenesis process by depending on the c-Myc pathway." (PMID 35546072, 2022). "However, we also showed an anti-cancer function of Fubp1 in certain circumstances." (PMID 32481602, 2020). "The NR_109/FUBP1/c-Myc axis regulates TAM polarization and remodels the TME to promote cancer development." (PMID 38769475, 2024). "Western blot analysis was first performed to analyse levels of endogenous CCAR1 and FUBP1 in normal and cancer cells lines, and results revealed increased expression of both CCAR1 and FUBP1 in cancer cells compared to normal." (PMID 36418423, 2022). "The increased interaction of CCAR1 and FUBP1 with Kpnβ1 in cancer cells confirms the mass spectrometry data and suggests that cancer cells may display an increased reliance on CCAR1 and FUBP1 nuclear function." (PMID 36418423, 2022). "Our analysis of the DNA methylation of FUBP1 demonstrated definitively low or no methylation in most cancer types analyzed in TCGA, except for UVM and PADD." (PMID 35274005, 2022). "Despite increasing evidence to support the relationship between FUBP1 and tumorigenesis in some types of cancers, there have been no analyses from a pan-cancer perspective." (PMID 35274005, 2022). "Western blot analysis validated the interaction of known and novel binding partners with Kpnβ1 and revealed enriched interactions between Kpnβ1 and select proteins in cancer cells, including proteins involved in cancer development, such as Kpnα2, Ran, CRM1, CCAR1 and FUBP1." (PMID 36418423, 2022). "Moreover, FUBP1 expression increased in several types of cancers, further exploring the role of FUBP1 and DVL1 on stemness transformation and metastasis in those cancers will broaden its significance." (PMID 34288405, 2021).
cancer (continued). "It has been reported that lncRNA SNHG1 could directly interact with FUBP1 central domain and resist the binding between FIR and FUBP1, thereby modulating the oncogene MYC transcription and promoting cancer development." (PMID 34116677, 2021). "Thus, it is well worth to examine if TAL1 or FUBP1 contribute to aberrant proliferation and differentiation in cancers, in which no obvious alterations in the loci of cell cycle and differentiation regulators themselves can be detected." (PMID 30653565, 2019). "Previous studies identified that far upstream element-binding protein 1 (FBP1), a transcriptional regulator of c-Myc that is one of the most frequently aberrantly expressed oncogenes in various human cancers, including NPC, is an important biomarker for many cancers." (PMID 26469968, 2015).
infection (2 papers, 2021 to 2023). The state of being infected such as from the introduction of a foreign agent such as serum, vaccine, antigenic substance or organism. "Quantitative RT-PCR and western blotting results demonstrated that the mRNA and protein levels of FUBP1 were notably increased in the 3 HCC cell lines after Lv-FUBP1 infection." (PMID 33954195, 2021).
kidney disease (1 paper, 2024). "Far upstream element–binding protein 1 (FUBP1) binds to the 3′UTR of polycystic kidney disease 2 (PKD2) mRNA to inhibit PKD2 translation." (PMID 38625739, 2024).
nervous system tumor (1 paper, 2012). "Our mutational analysis expands on recent reports that ATRX, CIC, and FUBP1 mutations are frequent in specific nervous system tumor types." (PMID 22869205, 2012).
reproductive system tumors (1 paper, 2022). "In addition, the expression of FUBP1 at the transcriptional level was not always consistent with that at the translational level, as observed in reproductive system tumors (OVs)." (PMID 35274005, 2022).
FUBP1 also shares sentences with these, for which no sentence is quoted: glioblastoma (5 papers); bladder urothelial carcinoma (2); CNS tumors (2); head and neck squamous cell carcinoma (2); lung squamous cell carcinoma (2); malignant glioma (2); melanoma (2); myeloid leukemia (2); non-small cell lung carcinoma (2); oligoastrocytoma (2); adenocarcinoma (1); B-cell non-Hodgkin lymphoma (1); bone tumor (1); breast invasive carcinoma (1); cardiac hypertrophy (1); central nervous system diseases (1); cholangiocarcinoma (1); chronic myelomonocytic leukemia (1); colon adenocarcinoma (1); diffuse large B-cell lymphoma (1); embryonal cancer (1); endocervical adenocarcinoma (1); esophageal adenocarcinoma (1); esophageal carcinoma (1); ganglioglioma (1); ganglioneuroblastoma (1); ganglioneuroma (1); glioneuronal tumors (1); gynecologic tumors (1); hematologic disorder (1).
A further 33 diseases each share a sentence with FUBP1 in 1 paper.